INS (insulin)
Diseases named in the same sentence as INS in open-access papers (continued):
Sharing a sentence is not in itself a finding about the gene and the disease.
diabetes (continued). "This work clearly demonstrates for the first time that hyperglycemia and decreased retinal insulin signaling each exert common and distinct effects on retinal pathophysiology, and that their combined disruptive effects contribute to increased retinal cell death during diabetes." (PMID 22046295, 2011). "In addition, insulin or glucose upregulated Egr-1 in vascular endothelial cells, suggesting that Egr-1 may play a role in the development of vascular complications from diabetes." (PMID 21365018, 2011). "A 54-year-old South Asian man (ID 13) who had revealed his diabetes to a peer indicated this had allowed him to improve the conditions for managing his diabetes at work: About six years ago I met another Surinamese guy, African Surinamese, who was also giving him self insulin injection." (PMID 21619571, 2011). "Therefore, the oligomannuronate-chromium (III) complexes could be used as potential anti-diabetes drugs for improving the insulin sensitivity." (PMID 21935427, 2011). "However the authors demonstrated that, although insulin expression was transiently induced in terminally differentiated hepatocytes, the long-term diabetes reversal obtained in these mice was resulting from the differentiation of hepatic progenitors able to generate islet-like clusters." (PMID 22007286, 2011). "However, more studies also including verified diagnoses of depression, both types of diabetes, patients from primary care settings, and patients with more severe treatment (i.e. insulin) should be conducted to approach the possibility of a different cut-off more thoroughly." (PMID 21791062, 2011). "Specifically, insulin use has a potential role in preventing IHD but may also be a risk factor for CVA among the diabetic elderly, thus revealing a need to develop improved treatment strategies for diabetes in elderly patients." (PMID 21978180, 2011). "Clinical trials have demonstrated the benefits of yoga in diabetes, hypertension, dyslipidemia, atherosclerosis, improving blood glucose, the insulin-glucose ratio, glycosylated hemoglobin, and requirements for oral hypoglycemics and insulin as well as body weight and composition." (PMID 21773016, 2011). "We have also identified eight important miRNAs (miR-144, miR-146a, miR-150, miR-182, miR-192, mir-29a, miR-30d and miR-320) that could participate in the regulation of insulin signaling as well as useful in distinguishing different stages of diabetes progression." (PMID 21829658, 2011). "Humans with mutations in the genes encoding for the transcription factors Hnf1α and Hnf4α develop similar forms of diabetes that result from abnormal insulin secretion, suggesting that the two factors might have related functions in insulin-producing islet-cells." (PMID 20523905, 2010). "This hypothesis postulates that the same genetic states that predispose one to diabetes also result in a quick insulin trigger even when the phenotype of diabetes is not expressed." (PMID 23908778, 2010). "Patients with diabetes mellitus, may require daily subcutaneous injections of insulin." (PMID 20492708, 2010). "Furthermore, the analysis at protein level shows that 88% of the direct relationships between diabetes effectors and the ketogenic-diet map are done by proteins related to the insulin resistance pathway, while proteins related to insufficient insulin production are less present." (PMID 21143928, 2010). "TLR4D299G/T399I associates with increased total body fat, visceral fat, liver fat and decreased insulin sensitivity in non-diabetic Caucasians and may contribute to diabetes risk." (PMID 21125016, 2010). "Although we did observe an association between the ADH1c (rs1693482) variant and IGT/diabetes as well as insulin sensitivity, the direction was opposite, and we could not confirm the results." (PMID 20700531, 2010).
diabetes (continued). "Although T2DM group was representative of the overall T2DM population in our medical center, these patients may have had more severe T2DM, as all of the T2DM patients in our study were treated with either insulin or oral medications for diabetes at the time when 25OHD was measured." (PMID 20946654, 2010). "Thus, IDE inhibitors with appropriate pharmacokinetic properties may be useful in combating diabetes by virtue of both “insulin sparing” and “insulin sensitizing” effects." (PMID 20498699, 2010). "Diabetes mellitus (DM) is a complex disease characterized by insufficient insulin production and resultant hyperglycemia with alterations in fat and protein metabolism." (PMID 20927192, 2010). "The physiological barriers to absorption of oral insulin, its low bioavailability and low biopotency, and the high inter-patient variability, are challenges that researchers need to overcome before oral insulin can be considered as suitable candidate for treatment of diabetes mellitus." (PMID 21059246, 2010). "Patients anticipate the early development of an oral insulin, as it will be easy to administer, have a lower index of intrusion, be more convenient, and have more compliance or adherence from the patient, and finally lead to better glycemic control, and thus, prevention of complications of diabetes." (PMID 21059246, 2010). "Thus, the use of insulin or OHAs could have artificially lowered hs-CRP levels in subjects with diabetes, making a difference between the groups difficult to detect." (PMID 20617007, 2010). "Thus, adolescents with TIDM should be involved in comprehensive teaching programs for self-management of diabetes and should be aware that the existing guidelines are useful, but the exact adjustments of insulin dose must be made on an individual basis with the help of their health care provider." (PMID 20652080, 2010). "In the present study, we found MyD88-deficient mice fed a HFD had increased circulating levels of insulin, leptin and cholesterol, as well as liver dysfunction (increased induction of ALT levels, increased activation of JNK and cleavage of PARP), which were linked to the onset of severe diabetes." (PMID 20824098, 2010). "Diabetes mellitus (DM) is a metabolic disorder characterized by hyperglycemia, insufficient insulin secretion, and receptor insensitivity to endogenous insulin." (PMID 20529353, 2010). "This led to the suggestion that GIPR antagonist may be useful in treating type 2 diabetes in European population where it is closely related to obesity and GIPR agonists may give a good indication with diabetes related to impaired insulin release, especially in Asia." (PMID 20673334, 2010). "Also ozone treatment partially reduce the imbalance between the generation of ROS and scavenging enzyme activity, while insulin may stimulate glucose transporters gene expression at the cellular level to control the hyperglycemic complications of diabetes." (PMID 20465785, 2010). "Screening of additional diabetic subjects for MPP7 mutations and generation of Mpp7 knockout mice are needed to test the hypothesis that this gene, and by inference abnormal islet cell polarity, play a role in impaired glucose-stimulated insulin secretion in MODY or other forms of diabetes mellitus." (PMID 19216786, 2009). "Thus altered expression of MPP7 in islets might affect cell polarity and impair glucose-stimulated insulin secretion, resulting in diabetes." (PMID 19216786, 2009). "We emphasize that if we obtain increased C-peptide levels for long periods and keep good glycemic control, we may offer patients a lower risk of chronic complications from diabetes, even without suspending insulin therapy." (PMID 19835616, 2009).
diabetes (continued). "If differences were found, we wanted to further examine whether these could be explained by demographic characteristics, lifestyle factors and cardiovascular disease status, in addition to diabetes-specific variables such as duration of diabetes, insulin use and long-term glucose control (HbA1c)." (PMID 19706152, 2009). "Interestingly, readjustment of the insulin administration normalized the drug metabolism as has been seen in experimental studies which highlights the importance of proper glycemic control to minimize the influence of diabetes on drug disposition." (PMID 19859566, 2009). "Unlike human patients with GLIS3 mutations, the medaka pc mutant shows none of the symptoms of a pancreatic phenotype, such as impaired insulin expression and/or diabetes, suggesting that the pc mutant may be suitable for use as a kidney-specific model for human GLIS3 patients." (PMID 19609364, 2009). "In a non-controlled study of ten Australian Aborigines with diabetes and a mean BMI of 27 kg/m2, O'Dea found that reversion to a hunter-gatherer lifestyle during 7 weeks led to 10% weight loss and reductions in fasting and 2 hour glucose and fasting insulin." (PMID 19604407, 2009). "Therefore, identifying and understanding the molecular functions of genes responsible for the control of fat metabolism and insulin sensitivity holds great promise for the development of pharmaceutical interventions for obesity and diabetes related health problems." (PMID 19503617, 2009). "According to the World Health Organisation, the term diabetes mellitus describes a metabolic disorder of multiple aetiology characterised by chronic hyperglycaemia with disturbances of carbohydrates, fat, protein metabolism resulting from defects in insulin secretion, insulin action or both." (PMID 19224650, 2009). "If present in arterial wall, this stimulation could result in increased tissue lipid accumulation, aggravating further the resistance to insulin of local glucose metabolism, and possibly contribute to the accelerated atherosclerosis of insulin-resistance and diabetes." (PMID 20030821, 2009). "Moreover, in addition to its role in the regulation of insulin release it will be important to define the possible involvement of RalA in other β-cell functions that when deregulated favour the development of diabetes mellitus such as apoptosis or proliferation." (PMID 19890390, 2009). "He had a 20-year history of type 2 diabetes mellitus (DM) that required insulin, with micro- and macro-vascular complications such as diabetic retinopathy and CKF." (PMID 19830164, 2009). "In conclusion, our data suggest that IL-8 is a main adipocytokine producing insulin resistance via the inhibition of insulin-induced Akt phosphorylation in human adipocytes, and the attenuation of IL-8 production and/or action may be a target for the prevention of diabetes and its complications." (PMID 19709445, 2009). "Hence, impaired insulin and IGF-1 signaling resulting in decreased GSK-3β (Ser 9) expression allows for phosphorylation of p-GSK-3β, a potent phosphorylating stress kinase, which has also been implicated in Alzheimer-like changes in diabetes." (PMID 19834568, 2009). "The precise mechanisms by which this gene affects diabetes risk are not known, but it is thought to influence insulin secretion, possibly through its role in the Wnt signalling pathway, and may also affect insulin resistance." (PMID 18291022, 2008). "However, the insulin-reactive CD8 T cells are capable of being highly pathogenic 14 and the ability to antagonize such cells and prevent them from causing early islet damage is likely to add benefit in protection against diabetes." (PMID 18157812, 2008). "Diabetic individuals fall into two distinct groups, those in which the disease is caused by a lack of insulin – known as insulin-dependent diabetes mellitus or IDDM – or by a certain resistance to the action of insulin, known as non-insulin-dependent diabetes mellitus or NIDDM." (PMID 18828926, 2008).
diabetes (continued). "However, oral agents such as glitazones have anti-inflammatory activity and could potentially also be an effective treatment for patients in the non-insulin dependent stage of their diabetes." (PMID 18652676, 2008). "We investigated an F2 intercross between the diabetes-resistant C57BL/6 leptinob/ob and the diabetes-susceptible BTBR leptinob/ob mouse strains that segregates for genotype and diabetes-related physiological traits; blood glucose, plasma insulin and body weight." (PMID 18369453, 2008). "Treatment of type 1 diabetes mellitus with insulin replacement is aneffective tool for addressing glucose metabolism, but it seems conceivable thatthe loss of C-peptide secretion from pancreatic beta cells might contribute tothe vascular complications in patients with diabetes mellitus type 1." (PMID 18670621, 2008). "This may be related to the decreased levels in diabetes of insulin and IGF1, which are both powerful activators of the mTOR pathway and which could act on the insulin-like growth factor receptor which is expressed on small and medium sized dorsal root ganglia neurons." (PMID 18398477, 2008). "In diabetics, as the insulin resistant state progresses, ASP resistance may be present as well." (PMID 17490487, 2007). "It is not yet clear whether it is insulin resistance or reduced insulin secretion that is responsible for the association between diabetes and cardiovascular disease." (PMID 17760500, 2007). "However, the relative importance of variations in fasting insulin, glucose, and glycated haemoglobin as risk factors for cardiovascular disease in women without diabetes is unclear." (PMID 17760500, 2007). "However, research is still needed to enhance our present understanding about factors responsible for the decreased Na+K+-ATPase observed in diabetes mellitus especially in Type 1 diabetes mellitus, which occurs early in life and requires life-long insulin therapy." (PMID 17908327, 2007). "Also significantly, insulin treatment had only a modest effect in maintaining podocyte number, despite inducing a substantial improvement in fasting blood glucose levels by 2 weeks after initiation of diabetes." (PMID 16539708, 2006). "However, a significant relationship was noted between the mean A1C of the child and the literacy level of the mother (r = 0.28; P = 0.01) after adjustment for the child's age and sex, duration of diabetes, daily insulin dose, the child's literacy score, and social class." (PMID 16907968, 2006). "Non-Hispanic African American women and Hispanic men treated with insulin and oral agents were disproportionately represented among those with poor glycemic control reported in a study using national survey data, possibly resulting in increased medical care costs for individuals with diabetes." (PMID 16776886, 2006). "Moreover, we determined whether early treatment with insulin or with the antioxidant, α-lipoic acid, resulted in preservation of podocyte density in animals with early diabetes." (PMID 16539708, 2006). "For example, randomized clinical studies demonstrate that moderate alcohol intake directly improves insulin sensitivity, perhaps by raising adiponectin levels, and hence differences in diabetes rates may be related to biological effects of alcohol consumption rather than confounding." (PMID 16670030, 2006). "African American women thought that a lack of physical symptoms indicated they no longer had diabetes, but concerns about diabetes were strongly linked to emotional factors, including fears about diabetes, denial, and concerns about insulin therapy and required lifestyle changes." (PMID 16164810, 2005). "Future safe and more effective anti-obesity medicines and insulin sensitizing agents that help to preserve β-cell function, in addition to efforts of lifestyle modification, thus hold promise for the overweight population with potential for reduction in the development of diabetics." (PMID 16232315, 2005).
diabetes (continued). "Background/Objectives: Type 2 diabetes mellitus (T2DM) is characterized by chronic hyperglycemia and insulin resistance, leading to progressive metabolic dysfunction." (PMID 41901353, 2026). "Additionally, population-level differences in pathophysiological mechanisms, such as variation in insulin resistance, beta cell function, fat distribution and the prevalence of specific diabetes subtypes, may influence how individuals respond to metabolic improvements." (PMID 41107618, 2026). "Technology-driven therapies for diabetes, including continuous glucose monitoring (CGM) and open-source automated insulin delivery systems (OS-AIDs), have revolutionised both diabetes care and research." (PMID 41247493, 2026). "Type 2 diabetes mellitus (T2DM) is characterised by impaired glucose homeostasis arising from insulin resistance and inadequate insulin action in peripheral tissues." (PMID 41732415, 2026). "For patients with diabetes who experience abnormal blood glucose fluctuations after ICI therapy, clinicians should monitor changes in endogenous insulin secretion and consider the possibility of hypoadrenocorticism." (PMID 41536580, 2026). "Over 90% of diabetic patients are diagnosed as having type 2 diabetes mellitus (T2DM), which is typically characterized by obesity, reduced insulin sensitivity, increased insulin secretion, and chronic inflammation in tissues." (PMID 41509193, 2026). "Type 2 diabetes mellitus (T2DM) is a chronic metabolic disorder characterized by insulin resistance and impaired insulin secretion, and curcumin-a polyphenolic compound derived from Curcuma longa-has shown potential anti-inflammatory and antioxidant effects." (PMID 42123439, 2026). "Further investigation revealed new-onset heart failure, diabetes, and hypercholesterolemia, prompting initiation of guideline-directed medical therapy (GDMT), insulin, and atorvastatin, respectively." (PMID 42005165, 2026). "Biochemical analysis revealed that diabetes induction reduced hippocampal BDNF and insulin levels and increased oxidative stress and inflammatory cytokines." (PMID 42222854, 2026). "There was some evidence for the carbohydrate last meal pattern lowering insulin levels and increasing GLP-1 and GIP levels in individuals with diabetes." (PMID 42045803, 2026). "This is unexpected as there is a correlation between ED-T1D and insulin omission, suboptimal glycemic outcome, recurrent DKA and consequent diabetes-related complications." (PMID 41484931, 2026). "One of the central features of type 2 diabetes mellitus (T2DM) is insulin resistance, where tissues such as skeletal muscle, liver, and adipose tissue become less responsive to insulin." (PMID 41346708, 2026). "All participants were on diabetes medications (metformin, SGLT2i, GLP‐1RA and/or insulin), with a majority on multiple agents (seven on one medication, seven on two medications and two on three medications)." (PMID 41251158, 2026). "Type 1 diabetes mellitus (T1DM) arises from an autoimmune process that targets and damages the insulin‐producing beta cells located within the islets of Langerhans in the pancreas." (PMID 41573056, 2026). "Type 2 diabetes mellitus (T2DM) is characterized by varying degrees of insulin resistance and impaired insulin secretion and can lead to renal dysfunction." (PMID 42227359, 2026). "Type 1 diabetes mellitus (T1DM), also known as insulin-dependent DM, generally results from the autoimmune destruction of insulin-producing pancreatic β-cells." (PMID 41601904, 2026). "By accurately identifying indicators such as insulin levels for Type 1 and Type 2 diabetes and POGTT results for Gestational diabetes, the system facilitates early diagnosis and supports proactive disease management." (PMID 41540069, 2026). "Metabolic disorders such as obesity and diabetes are influenced by glucagon-like peptide-1 (GLP-1), which regulates insulin secretion." (PMID 41723134, 2026).